LNCRI (lncRNA radiation induced regulator of PLK1 and RAD51)
Synonyms: lnc-RI
Gene: Long non-coding RNA gene on chromosome 7 (1,692,810 to 1,694,357, reverse strand). Ensembl gene ENSG00000205971.
Diseases named in the same sentence as LNCRI in open-access papers:
LNCRI is named in the same sentence as 1 disease in open-access papers, as found by Europe PMC text mining. Sharing a sentence is not in itself a finding about the gene and the disease.
LNCRI shares sentences with these, for which no sentence is quoted: cancer (1 paper).